H19 (H19 imprinted maternally expressed transcript)
Diseases named in the same sentence as H19 in open-access papers (continued):
Sharing a sentence is not in itself a finding about the gene and the disease.
bladder cancer (continued). "Long non-coding RNA H19 from the exosomes of M2 tumor-associated macrophages inhibits the interaction between ULK1 and its specific E3 ubiquitin ligase NEDD4L, stabilizing ULK1 expression and promoting autophagy in bladder cancer cells." (PMID 38027016, 2023). "The levels of lncRNA H19 are observed to plummet in bladder cancer tissues." (PMID 36359888, 2022). "Another example is H19, a well-known oncogenic lncRNA found in serum exosomes that was significantly upregulated in bladder cancer patients when compared to that of healthy individuals, which highlights its potential use as a biomarker for bladder cancer." (PMID 35269604, 2022). "Upregulated H19 is also responsible for promoting bladder-cancer cell migration." (PMID 36359888, 2022). "Higher levels of H19 were also found in serum exosomes from bladder cancer." (PMID 36188624, 2022). "This study extends our understanding of the regulatory mechanism of ULK1 and suggests that H19 in tumor microenvironment could be a potential target for bladder cancer treatment." (PMID 35607322, 2022). "However, H19 has been shown to reactivate during tumorigenesis and play a crucial role in various cancer including bladder cancer." (PMID 36685879, 2022). "In addition, studies have confirmed that lncRNA H19 is highly expressed in bladder cancer patients, and the expression level was 3 times higher than that in normal patients." (PMID 36406273, 2022). "In addition, H19 upregulated expression has been demonstrated to play a vital role in bladder cancer metastasis." (PMID 36685879, 2022). "Furthermore, it was reported that increased H19 expression accelerated cell proliferation by modulating ID2 expression in bladder cancer." (PMID 34421359, 2021). "The sixth CTCF-binding site may serve as a significant regulatory domain, thereby switching H19 or IGF2 expression in human bladder cancer." (PMID 34422802, 2021). "Another study showed that the association between the increased expression of H19 and EZH2 enhancers in patients with bladder cancer caused the stimulation of Wnt/p-catenin pathway, resulting in the down-regulation of E-cadherin, thus promoting the metastasis of bladder cancer cells." (PMID 34026626, 2021). "Recent studies revealed that lncRNA H19 could act as a sponge to inhibit miRNA‐29b‐3p in bladder cancer cells, colorectal cancer cells, and lung adenocarcinoma cells." (PMID 33463060, 2021). "A recent study demonstrated that H19 plays a vital role in bladder cancer invasion and metastasis." (PMID 34977037, 2021). "They found that lncRNA H19 in serum exosome was positively correlated with the H19 expression in paired bladder cancer tissues, and the level of lncRNA H19 in serum exosome in bladder cancer patients was higher than that in healthy subjects or patients with benign diseases." (PMID 34370713, 2021). "In summary, H19 played a vital in bladder cancer prognosis and could be the target of novel bladder cancer treatments." (PMID 34421359, 2021). "H19 increased bladder cancer metastasis by binding to EZH2 and inhibiting E-cadherin expression." (PMID 33267897, 2020). "H19 has also been shown to be a prognostic biomarker in bladder cancer." (PMID 33042838, 2020). "Bladder cancer patients with high level of exosomal H19 generally have poor survival." (PMID 32924276, 2020). "However, in other reports, H19 rs217727 has been linked to the risk of hepatocellular carcinoma (HCC), oral squamous cell carcinoma (OSCC), and bladder cancer in the Chinese population." (PMID 32523949, 2020).
bladder cancer (continued). "Additionally, higher urinary exosomal HOTAIR, MALAT1, PCAT-1, higher plasma exosomal H19, and higher serum exosomal UBC1 in NMIBC were associated with poorer prognosis of bladder cancer patients." (PMID 32517366, 2020). "Furthermore, levels of exosomal H19 are lower in healthy individuals and patients with benign disease compared with those with bladder cancer." (PMID 32924276, 2020). "The results of that study demonstrated that patients with bladder cancer carrying the H19 rs2839698 TC genotype, but not with the homozygous CC genotype, showed a significantly decreased risk of bladder cancer." (PMID 31013794, 2019). "The predictive results derived from our method inferred that ncRNAs H19 and WRAP53 might be associated with urinary bladder cancer." (PMID 29671405, 2018). "Such miR-29a-3p targeting might increase the expression of DNMT3B, VEGFA, and ITGB1 oncogenes, which suggested a possible involvement of H19 and circMYLK in the development, growth, and metastasis of bladder cancer." (PMID 29349062, 2017). "By example, H19 regulates EMT in bladder cancer by sponging miR-29b-3p." (PMID 29099749, 2017). "Furthermore, H19 upregulation is observed under hypoxia-induced stress in liver and bladder cancer cells." (PMID 29190892, 2017). "Similarly, bioinformatics approaches utilizing correlated coexpression networks of bladder cancer revealed a probable interaction between lncRNA H19 and circRNA circMYLK, demonstrating their ability to competitively bind to miR-29a-3p." (PMID 29349062, 2017). "Thus, in this study, we evaluated the possible regulatory role of H19-derived miR-675 in bladder cancer cell proliferation." (PMID 26198047, 2016). "H19 is one of the cancer-related lncRNAs, which has an oncogenic function and is strongly expressed in cancers, such as colorectal cancer, osteosarcoma, and bladder cancer." (PMID 27672656, 2016). "However, little is known about how miR-675, mature product of H19, contributes to bladder cancer cell proliferation." (PMID 26198047, 2016). "Upregulated H19 promoted the proliferation and metastasis of bladder cancer cells." (PMID 26198047, 2016). "This could indicate that H19 is involved at early time points in the invasion process in bladder carcinoma, such as in the response to hypoxia or EMT." (PMID 25101115, 2014). "Furthermore, another study has found that H19 was remarkably upregulated in bladder cancer tissues, and upregulated H19 promoted cancer cell migration both in vitro and in vivo by associating with EZH2 and inhibiting E-cadherin expression." (PMID 24379988, 2013). "Upregulated H19 contributes to bladder cancer growth by regulating ID2 expression." (PMID 24069260, 2013). "Our previous studies showed that H19 increases bladder cancer cell proliferation and metastasis." (PMID 24069260, 2013). "Ablations of tumorigenicity of HCC and bladder carcinomas in vivo are seen by H19 knockdown which also significantly abrogates anchorage-independent growth after hypoxia recovery, while ectopic H19 expression enhances tumorigenic potential of carcinoma cells in vivo." (PMID 17786216, 2007). "Therefore, lncRNA H19 may promote bladder cancer metastasis by combining with EZH2 and inhibiting the expression of E-cad." (PMID 36406273, 2022).
bladder cancer (continued). "Furthermore, H19 RNA level was greatly enhanced in tumor of human bladder cancer cells formed in nude mice and in patients with bladder cancer; it also could serve as a prognostic tumor marker for the early recurrence of bladder cancer." (PMID 26198047, 2016). "For instance, H19 was upregulated in bladder cancer and could promote cancer metastasis." (PMID 27806310, 2016). "Therefore, H19 appears to be an onco-lncRNA and serves as a tumor marker in bladder cancer." (PMID 24006935, 2013). "H19 gene was shown to be re-expressed in several cancer tissues derived from those tissues which expressed the gene during embryonic development, such as bladder cancer, hepatocellular carcinoma, adrenocortical tumors, choriocarcinoma, colorectal cancer, ovarian carcinoma, and lung carcinoma." (PMID 21052499, 2010). "To directly assess whether H19 expression was also essential for the growth of human bladder carcinoma cells in vivo, we first performed in vitro studies to determine whether siRNA H19 #1 that targets the H19 message, knocks-down H19 RNA in the human bladder carcinoma cell line, UMUC3." (PMID 17786216, 2007). "Urinary exosomes from 42 bladder cancer patients were collected and quantified for seven lncRNAs (UCA1, H19, MALAT1, TUG1, GAS5, RMRP, and LINC01517), showing increased expression of RMRP, UCA1, and MALAT1 in bladder cancer patients." (PMID 40075875, 2025). "lncRNA H19-silenced exosomes from TAMs led to a significant increase in the interaction between NEDD4L and ULK1, whereas lncRNA H19 overexpression suppressed the interactions between NEDD4L and ULK1 in bladder cancer cells." (PMID 37568787, 2023). "Irregular expression of HOTAIR, UBC1, H19, and GAS5 has been reported to be related to overall survival in bladder cancer however, more confirmative studies are needed to make a definite conclusion." (PMID 36685879, 2022). "H19 regulates the expression level of DNMT3B protein and epithelial-mesenchymal transition in bladder cancer." (PMID 34422802, 2021). "H19 promoter region can bind to CCCTC-binding factor (CTCF) and insulin like growth factor 2 (IGF2), and thereby regulating bladder cancer development in nucleus of BC cells." (PMID 34422802, 2021). "Human H19 promoter contains large amount of methylcytosine in the CTCF binding site of and is abnormal hypomethylated in human bladder cancer." (PMID 34422802, 2021). "Of these, XIST, H19, MALAT1, MEG3 play a role in tumor proliferation, suppression, and metastasis of bladder cancer." (PMID 31379598, 2019). "However, a systematic review of studies on the association between lncRNA SNPs and the overall risk of cancer suggested that the lncRNA H19 rs2839698 C/T and rs3024270 G/C polymorphisms, but not rs217727 C/T, are associated with overall cancer risk, including bladder cancer." (PMID 31013794, 2019). "Although previous data reported that H19 overexpression reduced ITGB3, ITGB5, and ITGA5 in bladder cancer cells and increased ITGB1 and ITGA1 in pancreatic cancer cells, the molecular mechanism by which H19 regulates integrin was not elucidated." (PMID 31426484, 2019). "It has been reported that miR-29b-3p was regulated by H19 and promoted EMT in both CRC and bladder cancer." (PMID 31164794, 2019). "The expression of H19, SNHG16 and UCA1 was significantly elevated in bladder cancer tissues, while PTENP1 and MEG3 were significantly decreased in bladder cancer tissues compared with adjacent normal tissues (P < 0.05)." (PMID 30285771, 2018). "This study showed that H19, SNHG16, UCA1, PTENP1 and MEG3 were aberrantly expressed in bladder cancer tissues." (PMID 30285771, 2018). "H19 was shown to interact with the histone methyl transferase Enhancer of zeste homolog 2 (EZH2) and epigenetically silenced E-cadherin in bladder cancer and DIRAS3 in diabetic cardiomyopathy." (PMID 29099749, 2017).
bladder cancer (continued). "Nuclear H19 binds EZH2, a key component of Polycomb repressive complex 2, and inhibits the transcription of a selective group of genes, thereby promoting bladder cancer metastasis." (PMID 27063004, 2016). "However, whether miR-675 involved in H19-mediated progression of bladder cancer remains unclear." (PMID 26198047, 2016). "However, little is known about whether H19-derived miR-675 regulates bladder cancer proliferation." (PMID 26198047, 2016). "As a matter of fact, another group previously demonstrated the H19 activated Wnt/β-catenin pathway by interacting with the RNA binding protein Enhancer of zeste homolog 2 (EZH2), leading to enhanced bladder cancer metastasis." (PMID 26853553, 2016). "Interestingly, another unexplored possible connection between oxidative stress and H19 promoted proliferation may be suggested from its proliferative effect in bladder cancer cells that was reported to be exerted by upregulation of Id2 (inhibitor of DNA binding/differentiation 2)." (PMID 26536864, 2015). "Thus, H19-driven and IGF2-P4-driven DTA-encoding sequences presented on a single expression vector (H19-DTA-P4-DTA), exhibited enhanced protein synthesis inhibition activity, relative to expression vectors carrying either DTA sequence alone when tested against bladder cancer cells." (PMID 21162716, 2010). "The double promoter construct H19-DTA-P4-DTA exhibited far superior efficiency in vitro, in lysing human bladder carcinoma cell lines, relative to each of the single promoter constructs carrying either DTA DNA sequence alone (H19-DTA or P4-DTA)." (PMID 21162716, 2010). "We used the double promoter construct, H19-DTA-P4-DTA assessing its tumor growth inhibition activity, by DTA expression in vivo using heterotopic and orthotopic animal models for bladder cancer." (PMID 21162716, 2010). "In this study we present an approach for targeted therapy of bladder carcinoma by driving the DTA expression under the control of IGF2-P4 and H19 regulatory sequences." (PMID 21162716, 2010). "By controlling oxygen pressure during tumor cell growth and H19 expression levels, we investigated the role of H19 expression in vitro and in vivo in hepatocellular (HCC) and bladder carcinoma." (PMID 17786216, 2007). "Of note, H19, UCA1 and SNHG15 have been recently studied in bladder cancer." (PMID 40461454, 2025). "It was reported that LncRNA H19 derived from TAMs could stabilize ULK1 expression by increasing the expression of LC3-II/I and decreasing SQSTM1/p62 levels, thereby activating bladder cancer cell autophagy." (PMID 39394189, 2024). "In bladder cancer, lncRNA RP11-79H23.3 and the tumor suppressor gene, Pt en, were significantly downregulated in bladder cancer tissues, inhibiting tumorigenesis, angiogenesis, and metastasis, like lncRNA H19." (PMID 35577352, 2022). "For example, higher urinary exosomal LNMAT2, higher urinary and serum exosomal circPRMT5, higher serum exosomal UCA1, the PCAT-1, UBC1, SNHG16 panel, higher plasma exosomal H19 and lower plasma exosomal PTENP1 were more frequently observed in bladder cancer patients than in healthy controls." (PMID 32517366, 2020). "This evidence demonstrated, for the first time, that H19 may function as a competing endogenous RNA (ceRNA) for miR-29b-3p and relieve the suppression of DNMT3B, leading to EMT and metastasis of bladder cancer." (PMID 33680956, 2020). "For example, lncRNA H19 promoted colorectal cancer progression by epigenetically repressing miR-200a, and LncRNA UCA1 contributed to tumor growth by down-regulating miR-16 in bladder cancer." (PMID 29212233, 2017).
bladder cancer (continued). "In a second example, H19 represses gene expression through the interaction with enhancer of zeste homolog 2 (EZH2), a H3K27 methyltransferase in a part of the polycomb repressive complex 2 (PRC2) in bladder cancer." (PMID 28933364, 2017). "Heterozygotes for the H19 rs2839698 TC intronal SNP are protected against bladder cancer, especially non-muscle-invasive bladder cancer." (PMID 29299175, 2017). "As the mature product of H19, our data showed that miR-675 was expressed at higher levels in bladder cancer tissues than in adjacent noncancerous tissues." (PMID 26198047, 2016). "Over-expression of H19 resulted in a significant increase in expression of ID2 (inhibitor of DNA binding/differentiation 2), whereas a knockdown of H19 expression decreased ID2 expression, suggesting that up-regulated H19 increases bladder cancer growth by regulating ID2 expression." (PMID 24006935, 2013). "Therefore we evaluated the feasibility of intravesical therapy of H19-DTA-P4-DTA, in nude mice orthotopic bladder cancer model." (PMID 21162716, 2010). "Therefore, we further investigated the combination use of H19 and IGF2 regulatory sequences for driving toxin gene expression in therapeutic vectors for bladder cancer treatment." (PMID 21162716, 2010). "LncRNAs H19 could be used as a valuable biomarker for HCC and bladder cancer." (PMID 31141943, 2019). "As a mature product of H19, miR-675 is the pivotal intermediator that H19 exploited to enhance the carcinogenesis and metastasis of different cancers; so, we further examined the regulatory role of H19 in miR-675 expression in 253J and RT4 bladder cancer cells." (PMID 26198047, 2016). "In addition, it was previously shown that in certain bladder carcinoma cell lines H19 RNA is either not or weakly expressed in normal culture conditions, but strongly expressed when tumors are grown by injecting these cell lines into nude mice." (PMID 19656414, 2009). "However, we found that the effects of miR-675 in RT4 cells were not apparent as in 253J cells; this may be owned to that 253J was invasive bladder cancer cells, while RT4 was noninvasive cells; the expressions of miR-675 and H19 were remarkably lower in RT4 cells." (PMID 26198047, 2016). "A panel of 96 target lncRNAs was used as a probe, some of which have been previously demonstrated to be involved in the development of bladder cancer or other tumors (UCA1, MALAT1, H19, and HOTAIR), while others have not yet been characterized." (PMID 38846969, 2024). "Two human bladder carcinoma cells lines, TA11 and TA31, originating from the same parental cell line, T24P, were either negative, (TA11H19-ve) or high expressers (TA31H19high) of H19, respectively." (PMID 17786216, 2007).